SLC12A3 (solute carrier family 12 member 3)
Description:
Electroneutral sodium and chloride ion cotransporter, which acts as a key mediator of sodium and chloride reabsorption in kidney distal convoluted tubules. Also acts as a receptor for the pro-inflammatory cytokine IL18, thereby contributing to IL18-induced cytokine production, including IFNG, IL6, IL18 and CCL2 (By similarity). May act either independently of IL18R1, or in a complex with IL18R1 (By similarity).
Synonyms: NCC; TSC; NCCT
Tractability: Small molecule: an approved drug acts on it; a structure with a bound ligand is known; it belongs to a druggable protein family. Antibody: UniProt places it where antibodies can reach, with high confidence; its Gene Ontology location is reachable by antibodies, with high confidence; UniProt predicts a signal peptide or a membrane-spanning region. PROTAC: UniProt records ubiquitination sites on it; ubiquitination databases record sites on it.
Target class: Electrochemical transporter; SLC superfamily of solute carriers; Transporter; SLC12 family of cation-coupled chloride transporters
Gene: Protein-coding gene on chromosome 16 (56,865,207 to 56,915,850, forward strand). Ensembl gene ENSG00000070915.
Subcellular location: Cell membrane; Apical cell membrane
Pathways (Reactome):
Disease: Defective SLC12A3 causes Gitelman syndrome (GS)
Transport of small molecules: Cation-coupled Chloride cotransporters
Gene Ontology:
Molecular function: protein binding; protein serine/threonine kinase binding; sodium:chloride symporter activity; sodium:potassium:chloride symporter activity; chloride:monoatomic cation symporter activity; sodium ion transmembrane transporter activity; transmembrane transporter activity
Biological process: renal sodium ion absorption; chloride transmembrane transport; chloride transport; potassium ion transmembrane transport; sodium ion transmembrane transport; sodium ion transport; monoatomic ion transport; response to aldosterone; response to salt; transmembrane transport
Cellular component: apical plasma membrane; extracellular exosome; plasma membrane; membrane; cytosol
Genetic constraint (gnomAD): Loss-of-function variants: 97 observed, 114.38 expected, observed/expected ratio (o/e) 0.85, 90% interval 0.72 to 1. The upper end of that interval is the gene's LOEUF score, 1, which puts it in group 4 of 6, group 1 being the genes least tolerant of losing a copy. Missense variants: 1,298 observed, 1,371.6 expected, observed/expected ratio (o/e) 0.95, 90% interval 0.9 to 0.99. Synonymous variants: 534 observed, 541.75 expected, observed/expected ratio (o/e) 0.99, 90% interval 0.92 to 1.06.
Homologues: Orthologues: chimpanzee SLC12A3 (99% identical), macaque SLC12A3 (97% identical), dog SLC12A3 (94% identical), pig SLC12A3 (93% identical), mouse Slc12a3 (90% identical), guinea pig SLC12A3 (90% identical), rat Slc12a3 (90% identical), rabbit SLC12A3 (82% identical), tropical clawed frog slc12a3 (75% identical), zebrafish slc12a3 (63% identical), Drosophila melanogaster Ncc69 (43% identical), Caenorhabditis elegans nkcc-1 (42% identical), and 4 more. Paralogues in human: SLC12A2 (53% identical), SLC12A1 (52% identical), SLC12A6 (28% identical), SLC12A7 (27% identical), SLC12A5 (27% identical), SLC12A4 (27% identical), SLC12A9 (21% identical), SLC12A8 (18% identical).
Diseases named in the same sentence as SLC12A3 in open-access papers:
SLC12A3 is named in the same sentence as 122 diseases in open-access papers, as found by Europe PMC text mining. Sharing a sentence is not in itself a finding about the gene and the disease. The quoted sentences say what the papers report.
Gitelman syndrome (124 papers, 2014 to 2026). Gitelman syndrome (GS), also referred to as familial hypokalemia-hypomagnesemia, is characterized by hypokalemic metabolic alkalosis in combination with significant hypomagnesemia and low urinary calcium excretion. "Gitelman syndrome (GS) is a rare, autosomal recessive salt-losing tubulopathy caused by mutations in the SLC12A3 gene." (PMID 41751411, 2026). "Gitelman syndrome (GS) is an autosomal recessive salt-wasting tubulopathy caused by pathogenic variants in SLC12A3, characterized by renal potassium wasting, hypokalemic metabolic alkalosis, hypomagnesemia, and typically low urinary calcium excretion." (PMID 41700263, 2026). "A subset of patients exhibiting clinical and biochemical signs consistent with Gitelman syndrome have been found to carry only monoallelic mutation in the SLC12A3 gene." (PMID 40777730, 2025). "Gitelman syndrome (GS) is a rare autosomal recessive salt-losing tubulopathy caused by mutations in the SLC12A3 gene, leading to hypokalemia, hypomagnesemia, hypocalciuria, and metabolic alkalosis." (PMID 40799897, 2025). "Gitelman syndrome (GS) is a rare hereditary electrolyte disorder caused by mutations in the SLC12A3 gene." (PMID 39792715, 2025). "Even deep intronic mutations in SLC12A3 which is responsible for some variants of Gitelman syndrome cannot be detected by WES." (PMID 40520344, 2025). "The 3 disorders with the highest lifetime risk (>1.5 per 100,000), accounted for 24% of the overall lifetime risk and were caused by PKHD1 (autosomal recessive polycystic kidney disease), SLC12A3 (Gitelman syndrome), and COL4A3 (Alport syndrome) variants." (PMID 40677321, 2025). "Adult-onset Gitelman syndrome is rare and is usually a result of a compound heterozygous mutation in the SLC12A3 gene, which results in loss of function of the gene." (PMID 40520344, 2025). "Gitelman syndrome is a rare autosomal recessive tubulopathy caused by mutations in the SLC12A3 gene, affecting the NCCT in the DCT." (PMID 40777730, 2025). "Genetic testing revealed 2 heterozygous mutations in the SLC12A3 gene: c.179C>T (p.T60M) and c.1077C>G (p.N359K), confirming the diagnosis of Gitelman syndrome." (PMID 40898507, 2025). "For example, for Gitelman syndrome, a common genetic tubulopathy caused by disease-causing variants in SLC12A3, the estimated prevalence in Asia is 1 in 40,000,23 comparable to our range of 1 in 43,860 (gnomAD European)." (PMID 40677321, 2025). "Whole-exome sequencing (WES) excluded pathogenic variants in renal tubulopathy genes including SLC12A3 (Gitelman syndrome), SLC12A1, CLCNKB, BSND, KCNJ1, MAGED2 (Bartter syndrome), and CASR, CLCNKA, KCNJ10 (hypokalemia-associated genes)." (PMID 40893942, 2025). "Gitelman syndrome (GS) is an autosomal recessive salt-wasting tubulopathy caused by biallelic inactivating mutations in the SLC12A3 gene, which encodes the thiazide-sensitive sodium-chloride cotransporter in the distal convoluted tubule." (PMID 40893942, 2025). "Gitelman syndrome (GS) is primarily caused by mutations in the SLC12A3 gene, leading to impaired function of the sodium-chloride cotransporter (NCC)." (PMID 39055258, 2024). "Further investigations, like genetic testing, showed a SLC12A3 gene mutation, a pathogenic homozygosity variant, proving the diagnosis of Gitelman syndrome." (PMID 39911369, 2024). "To date, more than 350 mutations distributed across the SLC12A3 gene have been identified in individuals with Gitelman syndrome (GS)." (PMID 39055258, 2024). "Gitelman syndrome (GS) is an infrequently encountered autosomal recessive condition, originating from mutations in the SLC12A3 gene encoding the thiazide-sensitive Na-Cl cotransporter." (PMID 39055258, 2024). "This study highlights the identification of two novel mutations within the SLC12A3 gene [c.421G>A: p.G141R and c.704C>A: p.T235K], contributing to the broader understanding of Gitelman Syndrome’s genetic diversity." (PMID 39055258, 2024).
Gitelman syndrome (continued). "By contrast, loss of function variants in the SLC12A3 gene in Gitelman syndrome are characterized by low blood pressure." (PMID 39595146, 2024). "Gitelman syndrome (GS) is a rare autosomal recessive salt-losing renal tubular disorder associated with a mutation of SLC12A3 or CLCNKB genes which encodes the thiazide-sensitive sodium-chloride co-transporter (NCCT) in the distal renal tubule." (PMID 37791211, 2023). "Gitelman syndrome is associated with loss-of-function variants in the SLC12A3 gene encoding the NCC." (PMID 37845702, 2023). "Genetic testing revealed compound heterozygous mutations in the SLC12A3 gene (c.506-1G > A, c.1456G > A) encoding the thiazide-sensitive sodium-chloride cotransporter, which presented a definitive diagnosis of Gitelman syndrome (GS)." (PMID 37131142, 2023). "Gitelman syndrome (GS) is an uncommon autosomal recessive tubulopathy resulting from a functional deletion mutation in the SLC12A3 gene." (PMID 38115360, 2023). "Gitelman syndrome is a rare salt-losing tubulopathy caused by inactivating mutations in the SLC12A3 gene, which is expressed in the distal convoluted tubule and accounts for 5–10% of renal sodium reabsorption." (PMID 40041278, 2023). "Three genes in EDS patients affect the kidney: the sodium chloride co-transporter SLC12A3 associated with Gitelman syndrome M263800, uromodulin UMOD associated with renal tubular disease M263800, and PKD1 associated with polycystic kidney disease M173100." (PMID 37504295, 2023). "Regarding Gitelman syndrome, it has been shown that it is caused by deactivating mutations in the SLC12A3 gene, which is responsible for thiazide-sensitive sodium–chloride cotransporter (NCCT) activity in the distal convoluted tubule." (PMID 37887299, 2023). "Gitelman syndrome (GS) is a type of salt‐losing tubular disease, most of which is caused by SLC12A3 gene variants, and missense variants account for the majority." (PMID 36597580, 2023). "Genetic testing focused to tubulopathies was performed and the diagnosis of Gitelman syndrome was made following the identification of two pathogenic variants in SLC12A3 gene (c.2633 + 1G>A and c.2221G>A)." (PMID 37351317, 2023). "In most recent screenings, approximately 75% of patients with a Gitelman syndrome presentation are diagnosed with a biallelic mutation in SLC12A3." (PMID 35894287, 2022). "Inactivating mutations in NCC (gene name: SLC12A3) result in Gitelman’s syndrome, a salt-wasting tubulopathy with hypokalemia, hypomagnesemia, metabolic alkalosis, and often (but not always) low blood pressure resulting from impairment in Na+ reabsorption." (PMID 35895103, 2022). "Classic Gitelman syndrome is caused by biallelic mutations in solute carrier 12 subtype 3 (SLC12A3) encoding the Na+-Cl−-co-transporter (NCC), which is exclusively expressed in the distal convoluted tubule (DCT)." (PMID 35894287, 2022). "The importance of NCC is apparent in patients with Gitelman’s syndrome, caused by inactivating mutations in the NCC-encoding SLC12A3 gene, whom usually present with hypotension, hypokalemia, hypomagnesemia, metabolic alkalosis, and hypocalciuria." (PMID 36160843, 2022). "Many clinical reports have demonstrated that the function-loss mutations in the SLC12A3 gene, mainly including Thr60Met, Asp486Asn, Gly741Arg, Leu859Pro, Arg861Cys, Arg913Gln, Arg928Cys and Cys994Tyr, play the pathogenic effects in Gitelman syndrome." (PMID 35591852, 2022). "Gitelman syndrome (GS) is an autosomal recessive disorder caused by SLC12A3 variants, and is associated with hypokalemia, hypomagnesemia, hypocalciuria, normal or low blood pressure, and salt loss." (PMID 35327948, 2022). "Gitelman Syndrome (GS) is a hereditary tubulopathy associated with a biallelic inactivating mutations of the SLC12A3 gene encoding the thiazide-sensitive sodium-chloride cotransporter (NCCT)." (PMID 35509038, 2022).
Gitelman syndrome (continued). "Most cases are caused by mutations in the SLC12A3 gene, and more than 140 different SLC12A3 mutations have been identified in patients with Gitelman syndrome." (PMID 33625696, 2021). "We aimed to evaluate renal tubular sodium (Na+) or potassium (K+) associated transporters expression from uEVs and kidney tissues in patients with Gitelman syndrome (GS) caused by inactivating mutations in SLC12A3." (PMID 34179047, 2021). "We identified a novel deletion variant of the SLC12A3 gene and discussed the appropriate hypoglycemic drugs in Gitelman syndrome (GS) patients with type 2 diabetes." (PMID 34348722, 2021). "Gitelman syndrome (GS) is an autosomal recessive tubulopathy caused by mutations of the SLC12A3 gene." (PMID 34348722, 2021). "Gitelman syndrome is typically caused by mutations in the SLC12A3 gene encoding the thiazide-sensitive NaCl cotransporter or the CLCNKB gene encoding the chloride channel ClC-Kb." (PMID 33625696, 2021). "Gitelman syndrome is a rare salt-losing renal tubular disorder associated with mutation of SLC12A3 gene, which encodes the Na-Cl co-transporter (NCCT)." (PMID 32758178, 2020). "Most SLC12A3 mutations in Gitelman syndrome are found as simple or complex heterozygous mutations, and few of them are homozygous." (PMID 32758178, 2020). "Gitelman syndrome is associated with dysfunction of NCCT protein encoded by SLC12A3 gene in the renal DCT." (PMID 32758178, 2020). "Whole-exome sequencing using DNA isolated from peripheral blood and the colonic adenocarcinoma revealed germline compound heterozygous mutations of c.179C > T and c.1326C > G in SLC12A3, consistent with her clinical diagnosis of Gitelman syndrome." (PMID 33024574, 2020). "In this study, we reported a Chinese pedigree of Gitelman syndrome with heterozygous compound mutations of SLC12A3, exhibiting hypokalemia and hypomagnesemia." (PMID 32758178, 2020). "In this study, we reported a Chinese familial Gitelman syndrome, and identified compound mutations of SLC12A3 with c.433C > T (p.Arg145Cys), c.1077C > G (p.Asn359Lys), and c.1666C > T (p.Pro556Ser)." (PMID 32758178, 2020). "Further efforts are needed to investigate the diversity in clinical manifestations of Gitelman syndrome and its correlation with specific SLC12A3 mutations." (PMID 32758178, 2020). "This systematic review was focused on searching an association between Arg913Gln variation in SLC12A3 gene with diabetic nephropathy in individuals with Type 2 Diabetes and Gitelman Syndrome." (PMID 31660880, 2019). "In contrast to BS type III, Gitelman syndrome is caused by mutations in a single gene, SLC12A3 (OMIM #263800), encoding the thiazide-sensitive sodium chloride co-transporter (NCCT) in the distal convoluted tubule." (PMID 30760291, 2019). "Gordon syndrome presents as a biochemical and phenotypic ‘mirror image’ of Gitelman syndrome, a salt wasting disease caused by inactivating mutations of SLC12A3 encoding NCC." (PMID 31795491, 2019). "The naturally occurring mutations found in the human SLC12A3 gene have been identified in patients suffering from a salt-wasting disorder called Gitelman's syndrome." (PMID 30515132, 2018). "Gitelman syndrome is an autosomal recessive disease mostly associated with loss-of-function mutations of the SLC12A3 gene and featured by clinical hypokalemia, hypomagnesemia, hypocalciuria, and histologically hypertrophy of the juxtaglomerular apparatus." (PMID 28469853, 2017). "Gitelman syndrome (GS) is a rare autosomal recessively inherited salt-wasting tubulopathy associated with mutations in the SLC12A3 gene, which encodes for NaCl cotransporter (NCC) in the kidney." (PMID 28446151, 2017). "Gitelman syndrome (GS), an inherited autosomal recessive salt-losing renal tubulopathy caused by mutations in SLC12A3 gene, has been associated with normal prostaglandin E2 (PGE2) levels since 1995 by a study involving 11 clinically diagnosed patients." (PMID 28700713, 2017).
Gitelman syndrome (continued). "Gitelman syndrome (GS) is an autosomal recessive, salt-losing renal tubulopathy caused by mutations in the SLC12A3 gene; however, it can also be acquired in patients with autoimmune disease, especially in those with Sjögren’s syndrome." (PMID 28819721, 2017). "Another example includes the SLC12A3 gene (Gitelman Syndrome), where 6% of the reported cases were caused by the presence of the abundant Alu sequences." (PMID 26966913, 2016). "Loss of function of mutated solute carrier family 12 member 3 (SLC12A3) gene is the most frequent etiology for Gitelman syndrome (GS), which is mainly manifested by hypokalemia, hypomagnesemia and hypocalciuria." (PMID 27783806, 2016). "Both mouse lines show a phenotype reminiscent of Gitelman’s syndrome, an autosomal recessive tubulopathy caused by inactivating mutations in the SLC12A3 gene coding for NCC." (PMID 26540196, 2015). "Familial hypocalciuric hypercalcemia (FHH) is an autosomal dominant disorder caused by an inactivating mutation in the CASR gene, while Gitelman syndrome (GS) is an autosomal recessive renal tubular disorder resulting from a pathogenic mutation in the SLC12A3 gene." (PMID 40070587, 2025). "Studies in knock-in mouse models of Gitelman syndrome (with SLC12A3 mutations) suggest that increased expression of TRPV5 and TRPV6 channels in the DCT may also contribute." (PMID 40777730, 2025). "Gitelman syndrome represents the most frequent tubulopathy diagnosed in this cohort: 6 patients (22%) carried pathogenic variants in SLC12A3 in the homozygous or compound heterozygous state, and satisfied criteria for a conclusive diagnosis of Gitelman syndrome." (PMID 37537162, 2023). "In accordance with this, Gitelman syndrome due to mutations in the SLC12A3 gene (MIM * 600968) encoding for the NaCl cotrasporter in the distal convoluted tubule usually has an adulthood onset with an incidental discovery of mild hypokalemia and hypomagnesemia with hypocalciuria." (PMID 37537162, 2023). "In addition to the RET c.1901G>A mutation, we found that the patients also had a novel variant in SLC12A3 (solute carrier family 12 member 3), which is highly associated with Gitelman syndrome (GS, OMIM# 263800)." (PMID 35627249, 2022). "Characteristics of SLC12A3 mutation among 10 patients with Gitelman syndrome." (PMID 34179047, 2021). "Gitelman syndrome (GS) is an autosomal-recessive disease caused by SLC12A3 gene mutations." (PMID 32702863, 2020). "The loss-of-function mutations in the SLC12A3 gene result in Gitelman syndrome." (PMID 32758178, 2020). "Gitelman syndrome (GS) is caused by biallelic mutations in SLC12A3 as an autosomal recessive trait." (PMID 32528714, 2020). "Furthermore, over 180 loss-of-function mutations have been identified in the SLC12A3 gene, encoding NCC, in relation to Gitelman syndrome (OMIM 263,800)." (PMID 30264650, 2018). "In addition, SPAK null mice recapitulate the phenotype of Gitelman syndrome (GS), inactivating mutations in SLC12A3 gene encoding NCC, with markedly diminished total and phosphorylated (p)-NCC expression." (PMID 26728390, 2016). "Gitelman’s syndrome (GS) is generally a distal convoluted tubule defect (DCT) caused by an inactivating mutation in the SLC12A3 gene that encodes the thiazide sensitive sodium chloride co-transporter (NCCT)." (PMID 26109196, 2015). "Mutations in SLC12A3 give rise to Gitelman's syndrome, a hereditary salt-wasting disorder." (PMID 25157616, 2014). "Likewise, although SLC12A3 p.Thr180Lys demonstrates functional pathogenicity in the context of Gitelman syndrome or ns-SNHL mimics, its high allele frequency may be explained by variable expressivity, incomplete penetrance, or late-onset progressive nature." (PMID 40592345, 2025). "The highest lifetime risk (> 1.5 per 100,000) was estimated for nephropathies caused by variants in PKHD1, SLC12A3, and COL4A3 associated with autosomal recessive polycystic kidney disease, Gitelman syndrome, and Alport syndrome, respectively." (PMID 40677321, 2025).